QKI (QKI, KH domain containing RNA binding)
Diseases named in the same sentence as QKI in open-access papers (continued):
Sharing a sentence is not in itself a finding about the gene and the disease.
cancer (continued). "GO and KEGG analyses were used for the evaluation of various genes, such as QKI, EGFR, and RGS12 that are closely associated with the incidence of cancer." (PMID 35068348, 2022). "Using in silico drug/gene perturbation combined screening, we discovered that QKI-overexpressing cancer cells are selectively vulnerable to CDC42-PAK7 inhibition by statins." (PMID 36672609, 2022). "By integrating large-scale genome-wide methylation data of multiple cancer types from TCGA, we discovered that the QKI promoter was specifically hypermethylated in the CRC tissues but not in other cancer types or adjacent normal tissues." (PMID 36017498, 2022). "Quaking (QKI), an RNA-binding protein, has been reported to exhibit numerous biological functions, such as mRNA regulation, cancer suppression, and anti-inflammation." (PMID 32382069, 2020). "QKI affects mRNA turnover in various diseases including cancer and for the generation of circRNA, there is a requirement for a specific RBP binding site within introns." (PMID 32467674, 2020). "Pathway enrichment analysis showed that QKI splicing targets were enriched in tight junction pathway, endocytosis and MAPK signaling pathways, all of which are highly associated with cancer development and progression." (PMID 32273884, 2020). "In order to investigate the effects of QKI on the biological behavior of cancer cells, we overexpressed and knocked down QKI in the 786-0 and caki-1 cell lines, and verified the efficiency of the expression manipulation in the 786-0 cell line." (PMID 32047543, 2020). "For example, QKI showed positive correlation with the biogenesis of circRNAs in six cancer lineages." (PMID 31446897, 2019). "While seeking to identify the miR‐200 targets most biologically relevant to cancer progression, we surprisingly found that QKI is one of the most consistent clinical correlates of miR‐200 activity." (PMID 29871889, 2018). "The genes for which we identified QKI binding sites proximal to the splice sites by QKI‐HITS‐CLIP were predominantly in the conserved cluster, reinforcing the conclusion that QKI influences alternative splicing in all of these cancers." (PMID 29871889, 2018). "Remarkably, 10 of these genes exhibit highly conserved QKI‐responsive splicing changes across all cancer types (shown in red)." (PMID 29871889, 2018). "Here, we show that miR‐200c and another epithelial‐enriched miRNA, miR‐375, exert widespread control of alternative splicing in cancer cells by suppressing the RNA‐binding protein Quaking (QKI)." (PMID 29871889, 2018). "We also performed GO analysis on the set of genes whose alternative splicing was consistently affected by QKI in different carcinomas, which confirmed that regulation of the actin cytoskeleton was the function most affected by QKI." (PMID 29871889, 2018). "But circRNAs formation is regulated by QKI proteins, providing a novel perspective to QKI-mediated circRNAs therapeutic strategies in cancer." (PMID 28969093, 2017). "Some of the switch factors controlling macroH2A1 splicing into macroH2A1.1 or macroH2A1.2 isoforms have been identified in cancer cells: QKI and RNA helicases Ddx17/Ddx5." (PMID 27800025, 2016). "Specific splicing regulators, including RBFOX2, MBNL1/2 and QKI, appear to account for many splicing alteration events in multiple cancer types." (PMID 25908786, 2015). "MBNL1/2, RBFOX2 and QKI were downregulated in most of the cancer types and, as expected, their motifs were enriched in these cancer types upstream to exons with higher exclusion and downstream to exons with higher inclusion in cancer." (PMID 25908786, 2015). "We found a significant enrichment of consensus binding sites of PTB, CELF, RBFOX and MBNL in the upstream introns, and RBFOX, QKI and MBNL in the downstream introns flanking the cancer associated cassette exons in more than one cancer type (FDR = 0.01)." (PMID 25908786, 2015).
cancer (continued). "Nevertheless, these results further support the association between QKI and RBFOX2 and alternative splicing in the indicated cancers." (PMID 25908786, 2015). "We further examined whether the inhibitory effects of QKI-6 on cancer cell proliferation and migration depend on PABPN1 LLPS." (PMID 40052530, 2025). "The role of QKI in malignant tumors is garnering increasing attention." (PMID 39479357, 2024). "Compaction of the Golgi apparatus has been reported to occur during EMT and to aid cancer cell migration and metastasis, and it may be that QKI also has a role in regulating this phenomenon." (PMID 38019605, 2024). "Consequently, elucidating the regulatory network and mechanism of QKI, including its upstream and downstream effectors, is instrumental in exploring its potential value in the diagnosis and treatment of malignant tumors." (PMID 39479357, 2024). "To determine whether this observation is broadly consistent in other contexts, we conducted a survey of QKI isoform expression across the Genotype-Tissue Expression (GTEx) and the Cancer Cell line Encyclopedia (CCLE) datasets." (PMID 38019605, 2024). "In malignant tumors, the methylation of the QKI promoter inhibits its expression." (PMID 39479357, 2024). "Moreover, QKI knockdown reduced the clonogenicity in PANC-1 cells, a feature associated with metastatic colonization by cancer cells, whereas its up-regulation in HPAF-II increased clonogenicity." (PMID 38325381, 2024). "QKI has been proven to participate in the development of cancer by regulating circRNAs." (PMID 37428781, 2023). "Moreover, the QKI promoter was specifically hypermethylated in cell lines of CRC (n = 49) compared with cell lines of other cancer cell lines (n = 908)." (PMID 36017498, 2022). "Furthermore, QKI overexpressing cancer cells were selectively sensitive to the HMGCR inhibitor fluvastatin." (PMID 36672609, 2022). "A series of recent work has further demonstrated that QKI has important roles in much broader biological systems, such as cardiovascular development, monocyte to macrophage differentiation, bone metabolism, and cancer progression." (PMID 34222237, 2021). "QKI was identified as a key regulator of alternative splicing in cancers." (PMID 32952599, 2020). "Studies found that QKI could inhibit the proliferation and tumorigenesis in multiple cancer types such as colon cancer, gastric cancer, lung adenocarcinoma, and renal cell carcinoma." (PMID 32194406, 2020). "And the mRNA and protein levels of QKI were measured in four cancer cell lines." (PMID 32194406, 2020). "Our previous studies demonstrated significant role of QKI in cancers 14-17." (PMID 32047543, 2020). "Pathway enrichment results showed that all these influenced splicing target events of QKI were enrolled in cancer development and progression related pathways, including tight junction pathway, transcriptional mis-regulation in cancer, endocytosis, and MAPK signaling pathways." (PMID 32273884, 2020). "To assess whether the influence of QKI on splicing in cancer extends to carcinomas more generally, we repeated the analysis on seven epithelial cancers for which there are at least 450 samples present in the TCGA." (PMID 29871889, 2018). "Together, these data demonstrate a consistent relationship between miR‐200c and QKI in diverse experimental and clinical data sets, suggesting miR‐200c may directly target QKI, with consequences for cancer progression." (PMID 29871889, 2018). "Therefore, a better understanding of miR-155/QKI functions and their control of expression in immune cells should allow to design new miR-155-based cancer immunotherapies." (PMID 26337206, 2015). "Perhaps a similar mechanism, described for QKI, may be observed in other types of cancer." (PMID 38542080, 2024). "Additionally, QKI plays diverse roles in the progression of cancers." (PMID 39479357, 2024). "Several studies have reported that QKI may have dual roles in cancer." (PMID 33262952, 2020).
cancer (continued). "We have expanded upon the knowledge in the field by demonstrating that the overlapping action of QKI and RBFOX2 is not limited to cancer but is also an active regulatory mechanism in muscle." (PMID 40207498, 2025). "YY1 was shown to bind SEs driving QKI, RAE1, FOXC1, and MET1 transcription in HCC, HGSOC, and TNBC, respectively, which positively affects cancer-cell migration and invasion (Table A1)." (PMID 38542080, 2024). "The methylation levels of 10 CpGs in the QKI promoter were significantly higher in CRC than in normal tissues and other cancer types." (PMID 38336771, 2024). "Thus, QKI may play an important role as an oncogenic factor in the development of malignant tumors." (PMID 36831493, 2023). "As expected, methylation of the QKI promoter remains robust in diagnosing CRC, even in the early stages of cancer." (PMID 36017498, 2022). "It has been revealed that RBPs such as QKI, AGO, Pol II and MBL can bind to circRNAs and RBP misregulation of gene transcription or expression plays an important role in cancer progression." (PMID 28969093, 2017). "Opposite trends of expression changes were observed for QKI, MBNL1 and CELF2 in the KIRC compared to other cancer types (upregulation in KIRC versus downregulation in other cancer type)." (PMID 25908786, 2015). "We show that many of these events are shared among different cancer types; our data also suggest that specific splicing factors, namely RBFOX2, QKI, MBNL1/2, PTBP1 and CELF2 are probably responsible for many of the alterations detected in these cancer types." (PMID 25908786, 2015). "However, the functional targets of QKI in cancers are largely unknown." (PMID 24722255, 2014). "On the other hand, even for splicing factors with clear functional relevance, such as QKI and ESRP1, target genes of the same splicing factor may impose opposite effects on cancers in a context-dependent manner." (PMID 39550559, 2024). "QKI‐5 could selectively bind to the QKI response element (QRE, 5′‐A[C/A]UAA‐3′) on cancer‐related genes, such as ß‐catenin." (PMID 36172919, 2023). "Complementing this, our study demonstrates that a region of the QKI gene (chr6: 163,834,452–163,834,924) has similar robustness in distinguishing CRC from normal tissues and is a CRC-specific methylation marker relative to 30 other types of cancer." (PMID 36017498, 2022). "Integrating large-scale datasets of multiple cancer types, our genome-wide methylation analysis identified that QKI was specifically hypermethylated in CRC tissues but not in other cancer types." (PMID 36017498, 2022). "We used GO and KEGG analysis to analyze many cancer-related genes, including QKI, CTNNA1, GSK-3b, and RGS12, which had not been previously identified in HCC." (PMID 35068348, 2022). "Similarly, during epithelial to mesenchymal transition (EMT) another RBP, Quaking (QKI) belonging to STAR (signal transduction and activation of the RNA) family during cancer metastasis plays a role in circRNA biogenesis." (PMID 32467674, 2020). "This opposite splicing regulation in KIRC, may result –in part- from the opposite change in level of expression of QKI, MBNL1 and CELF2 that we detected in KIRC compared to other cancer types." (PMID 25908786, 2015). "Recent research has revealed that the QKI protein, which is downregulated in a spectrum of malignant tumors such as lung, gastric, and CRC,314–317 and serves as a tumor suppressor in various human cancers, encompassing oral, colon, gastrointestinal, and prostate cancer." (PMID 40675967, 2025).
neurological diseases (7 papers, 2017 to 2022). "Previously, QKI is known for its important disease-causing contribution to human diseases, especially the neurological disorders, such as schizophrenia, 6q terminal deletion syndrome, myelin disorders, and Alzheimer’s disease (AD)." (PMID 34222237, 2021). "As QKI is one of the genes most associated with various neurological diseases, understanding the mechanisms underpinning Qki/Srebp2-mediated cholesterol biosynthesis and myelination will help identify tissue-specific therapeutic opportunities for neurological diseases associated with myelin defects." (PMID 33942715, 2021). "QKI is expressed in the central nervous system during embryonic development and is involved in human diseases, particularly neurological disorders, such as schizophrenia and Alzheimer’s disease." (PMID 34943825, 2021). "The involvement of SIRT2 in QKI-related neurological diseases is gaining increased attention." (PMID 34943825, 2021). "Previously, QKI has been known for its important role in contributing to neurological disorders." (PMID 34222237, 2021). "In mice, QKI depletion induced rapid demyelination and neurological disorders." (PMID 34063504, 2021).
cardiovascular diseases (5 papers, 2016 to 2023). "Although this genetic association will need further confirmation, the close association of QKI in cardiovascular diseases and the unique isoform-specific function of QKI among different cell types that shape the cardiovascular system have been recognized." (PMID 34222237, 2021). "QKI links intracellular signaling to cellular survival and QKI dysregulation is implicated in several cardiovascular diseases." (PMID 31191799, 2019). "Our work finds that QKI is potentially involved in the pathogenesis of certain forms of cardiovascular diseases." (PMID 33397958, 2021). "These emerging findings not only provide a critical understanding of QKI as an important regulator in pre-mRNA processing but also reveal its potential contribution to the pathogenesis of cardiovascular diseases and potential use as a therapeutic target in treating these diseases." (PMID 34222237, 2021). "Altogether we propose that QKI is involved in inflammatory responses to injury and could be a potential thrapeutic target to prevent cardiovascular disease." (PMID 26950853, 2016). "QKI is known to be involved in cell cycle regulation, a pathway for which there is emerging evidence for a key role in developing atherosclerotic plaques and cardiovascular disease." (PMID 26950853, 2016).
infection (5 papers, 2016 to 2025). The state of being infected such as from the introduction of a foreign agent such as serum, vaccine, antigenic substance or organism. "Worthy to note that the levels of AKT and mTOR are increased in QKI deficiency macrophage after infection, it indicated that the increased pathogen removal effects were independent on the classical mTOR pathway." (PMID 36088389, 2022). "Taken together, the up-regulated Rnf6 post-infection promoted QKI degradation and facilitated the release of PI3K-p110β mRNA from P body to activate translation, ending up with its higher expression and the enhanced autophagy." (PMID 36088389, 2022). "In order to identify the interacting E3 ubiquitin proteins tagged for QKI in macrophage after MRSA-infection, the co-immunoprecipitation analysis was performed." (PMID 36088389, 2022). "Meanwhile, QKI deficient RAW 264.7 cells showed increased secretion of pro-inflammatory cytokines, such as TNF-α, IL-6, IL-1β, and decreased secretion of IL-10, post-infection." (PMID 36088389, 2022). "This is the first time to disclose QKI was mainly present in the P body region of macrophages at rest state and QKI reduction facilitated the target mRNA transporting to the translational machine to enhance Xenophagy process in post-infection." (PMID 36088389, 2022). "This study disclosed the novel function of QKI in the P body mRNA regulation during infection." (PMID 36088389, 2022). "QKI reduction by shRNA or infection facilitated the release of PI3K-p110β mRNA from P body." (PMID 36088389, 2022). "Moreover, ubiquitinated QKI was primarily in the cytoplasm of RAW264.7 cells after infection." (PMID 36088389, 2022). "Furthermore, a reduction in QKI expression also appeared to influence T-cell and Toll-like receptor signalling, biological processes that play prominent roles in the rapid resolution of infection, while in chronic settings exacerbate inflammatory conditions." (PMID 27029405, 2016). "Upon infection, the direct interaction of RNF6, a RING-type E3 ligase, mediated QKI ubiquitination degradation and facilitated PI3K-p110β related autophagic removal of pathogen." (PMID 36088389, 2022). "To quantify a dependency between the amount of QKI overexpression and resulting subcellular localization, we transduced neonatal rat cardiomyocytes with AAV2 Qki5 at MOI (multiplicity of infection) of 5*103 (low dose) and 1*105 (high dose)." (PMID 29133306, 2018). "Then we observed the dot-like staining of QKI in the cytoplasm, there’re co-localizations of QKI and EDC4 (P-body biomarker) in the cytoplasm of RAW264.7 cells, and the QKI was dramatically decreased after infection." (PMID 36088389, 2022). "Moreover, the level of autophagy was increased after infection, and there was more co-localization of bacteria and LC3-II immunostaining, indicating the autophagy involved in anti-bacteria process, which was enhanced after QKI deletion." (PMID 36088389, 2022). "In addition, as scanning electron microscopy (SEM) analysis results shown, compared with the controls, QKI silencing increased the numbers of autophagosome-like vacuolar structures even without infection." (PMID 36088389, 2022). "The co-immunoprecipitation analysis showed that Rnf6 could interact with QKI in macrophages regardless of infection." (PMID 36088389, 2022).
cardiac disease (4 papers, 2019 to 2023). "This is particularly relevant, as there is evidence that QKI expression is lost during multiple forms of heart disease." (PMID 36627242, 2023). "Taken together, this indicates an important role for both QKI and PUM2 in fibrotic cardiac disease." (PMID 31284728, 2019).
psychiatric disorder (3 papers, 2017 to 2024). A disorder characterized by behavioral and/or psychological abnormalities, often accompanied by physical symptoms. "Reportedly, QKI plays a specific role in myelin defects in the aetiology of psychiatric disorders and is critical to the myelination decision of the OL in MDD suicide victims." (PMID 38281050, 2024). "Besides connecting FEZ1 with TFs that are dysregulated in psychiatric disorders, our studies also identified FEZ1 as a downstream target of QKI-dependent post-transcriptional regulation, which is essential for OL differentiation and myelinogenesis." (PMID 29249816, 2017).
CNS tumors (2 papers, 2021 to 2024). "In addition, QKI, a recognized fusion partner common in angiocentric glioma, was generally up-regulated in these 14 cases, compared to a cohort comprising >1000 CNS tumors of various types, regardless of whether a genomic alteration in QKI was present." (PMID 39422766, 2024).
metabolic disease (2 papers, 2018 to 2024). A congenital disorder (due to inherited enzyme abnormality) or acquired (due to failure of a metabolically important organ) disorder resulting from an abnormal metabolic process. "Recently, QKI has been linked to the pathogenesis and pathophysiology of some metabolic diseases (especially the type 2 diabetes and obesity) in mammals, highlighting its important roles in normal physiology and metabolic disorders." (PMID 29740344, 2018).
bacterial infections (1 paper, 2021). "QKI, as an RNA binding protein, was related with inflammatory responses in bacterial infections by regulating the polarization of macrophages." (PMID 33758177, 2021).
digestive diseases (1 paper, 2024). "This review will focus on the latest research progress on the roles of m7G methyltransferase METTL1/WDR4 and recognized enzyme QKI in digestive diseases." (PMID 39850560, 2024).
kidney (1 paper, 2020). "Taken together, these data suggest that reduction of QKI expression leads to reduced macrophage influx and subsequently reduced interstitial fibrosis of the kidney." (PMID 34968236, 2020).